MMP11 (matrix metallopeptidase 11)
Diseases named in the same sentence as MMP11 in open-access papers (continued):
Sharing a sentence is not in itself a finding about the gene and the disease.
tumor (continued). "In a more recent study, we found that MMP-11 (also known as stromelysin 3) expression by MICs, and TIMP-2 expression by CAFs, either at the tumor center or at the invasive front, were the most potent independent prognostic factors for predicting the clinical outcome of patients." (PMID 31086100, 2019). "Ectopic expression of miR-125a may down-regulate MMP11 and VEGF in vitro and in vivo supporting its role as tumor suppressive miRNA; inhibiting the proliferation, invasion and metastasis of HCC." (PMID 29534065, 2018). "Our study highlights miR-135a was an androgen-induced tumor suppressor that might be downregulated by androgen depletion, thus up-regulating RBAK and MMP11 promote PCa progression." (PMID 27323416, 2016). "In addition to MMP2 and MMP9, we investigated the expression of MMP3, MMP11, MMP13 and MMP14 in tumour cells." (PMID 26284589, 2015). "A limitation of our study is the restricted data set and the lack of match between MMP11 tumor expression and plasma samples within the same patients population." (PMID 24564996, 2014). "Our data strongly suggest that the tumor suppressing effects of miR-98 may be mediated by inhibitingthe ALK4 and MMP11 signaling pathways." (PMID 23211491, 2012). "These latter factors were analyzed in a wider tumor sample, in which we confirmed the higher expression of those factors in tumors infiltrated by MMP-11 positive MICs and that the expression not depend of only one cell type." (PMID 23145063, 2012). "MMP-11 is a member of the MMP family that degrades ECM components and may play a central role in the enhancement of tumor-induced angiogenesis, cell migration, proliferation, apoptosis and connective tissue degradation." (PMID 21513571, 2011). "Collagen IV and V appeared to be ideal candidates for further analysis of MMP induction as they are present in the basement membrane and would therefore be released specifically during early tumour invasion and metastasis, which coincides with MT1-MMP and MMP-11 expression in vivo." (PMID 15272933, 2004). "Besides overexpression of MMP7, a known β-catenin-dependent target gene in colon cancer, the results show an overexpression of MMP1, MMP3, MMP11, MMP12 and MMP13 in desmoid tumours compared to normal fibroblasts (fascia tissue)." (PMID 15054469, 2004). "Expressed in stromal fibroblasts adjacent to epithelial tumour cells, the mechanism of MT1-MMP and MMP-11 induction remains unknown." (PMID 15272933, 2004). "We investigated MMP11’s impact on the PCa TME and observed that MMP11- high expression correlated with increased infiltration of Tregs and M2 macrophages—key immunosuppressive populations driving tumor progression, immune evasion, angiogenesis, and therapy resistance." (PMID 40607407, 2025). "MMP-11 has also a significant role in tumor cell survival rather than in proteolytic action, which may be another reason for the high expression of MMP-11 in BC progression." (PMID 37798646, 2023). "The expression levels of tumor cell PD-L1 were higher in the MMP11-positive expression group than in the MMP11-negative expression group, and the proportion of PD1+CD8+ T cells infiltrated was reduced in the MMP11-positive group compared to the MMP11-negative group." (PMID 36756152, 2023). "MMP-11 is also a negative modulator of pre-adipocyte differentiation and reverses the differentiation of mature adipocytes, which leads to the peritumoral accumulation of fibroblast-like cells, thus favoring tumor progression." (PMID 35163727, 2022). "Differential gene expression analysis by Seurat34,35 identified 160 genes uniquely upregulated in tumor cells compared with TAF and normal kidney, including genes previously reported (e.g., GPNMB8, SQSTM1/p6236, MMP237, PTGDS38) and genes involved in tumor metastasis (e.g. MMP11, MDK, DCN, PDPN)." (PMID 36028490, 2022).
tumor (continued). "MMP11 accelerated the degradation of serine protease inhibitor α1-antitrypsin and insulin-like growth factor binding protein-1 (IGFBP-1), induced differentiation of a desmoplastic reaction surrounding the cancer stroma through cleavage of collagen VI and stimulated tumor progression and metastasis." (PMID 33920789, 2021). "We could see that about half MMPs are highly expressed in tumor tissues as compared with normal tissues, including MMP9, MMP10, MMP11, MMP12, MMP15, MMP25, MMP26 (all, P<0.05), while some other MMPs decreased in tumor tissues, including MMP2, MMP14, MMP16, MMP24, MMP28(all, P<0.05)." (PMID 32669958, 2020). "In addition, these results support the implication of MMP11 expression by inflammatory cells, but not by fibroblasts, in the context of dynamic tumor-stroma interactions, and its relationship with clinical outcome." (PMID 33396463, 2020). "This could indicate that MMP11 expression may depend on the response of the patient and not on the characteristics of the tumor." (PMID 33396463, 2020). "Only the expression of COL10A1 and MMP11 was found to progress from ‘low expression’ in pDCIS, to ‘intermediate expression’ in DCIS and ‘high expression’ in the corresponding IBC, the difference between pDCIS and DCIS (of DCIS/IBC mixed tumours) being significant (P < 0.05)." (PMID 30236106, 2018). "In the present study, we demonstrated that as an androgen-induced tumor suppressor, miR-135a decreased PCa cells proliferation and induced PCa cell cycle arrest and apoptosis through its target RBAK, and repressed cell migration by down-regulating the expression of MMP11." (PMID 27323416, 2016). "However, both CD147 and MMP-11 expression was not correlated with patient’s gender, age, differentiation, tumor size, and depth of invasion." (PMID 26507719, 2015). "MMP-11 differs from other MMPs, which are expressed as proenzymes and processed to active forms through proteolytic cleavage activated extracellularly, indicating that MMP-11 could have a unique role in tumor development and progression." (PMID 21513571, 2011). "However, MMP-11 expression is a characteristic of tumours of epithelial origin that is not found in lymphoid neoplasia." (PMID 8645587, 1996). "Indeed, MMP11 is secreted in its active form, unlike other MMPs, which are first expressed as proenzymes; thus, MMP11 may have a unique function in tumor development, although it does not degrade major ECM components." (PMID 41228294, 2025). "Interestingly, MMP-11 immunohistochemical score did not correlate with tumor size, nodal status." (PMID 38438841, 2024). "MMP-11, primarily expressed by CAFs, targets non-ECM substrates such as α1-antitrypsin, indirectly promoting ECM remodeling and tumor cell migration." (PMID 40906383, 2025). "MMP1 and MMP11 do not appear to be upregulated in PBMC; however, our previous results demonstrate that MMPs are highly expressed by tumor infiltrated cells and also by surrounding sentinel lymph nodes cells in aggressive BC." (PMID 33396463, 2020). "We found that ST3 (MMP11) is positively related to PINCH expression in CRC (unpublished data), and, both ST3 and PINCH are present in stromal fibroblasts around tumour cells but not in tumour cells themselves." (PMID 17026740, 2006).
cancer (190 papers, 1992 to 2025). A tumor composed of atypical neoplastic, often pleomorphic cells that invade other tissues. "Targeting MMP11 in cancer-associated fibroblasts reversed their pro-tumorigenic effects on PCa progression." (PMID 40607407, 2025). "Despite this variability, survival analysis indicated that MMP11+ mCAFs were consistently associated with poor prognosis across all four cancer types." (PMID 40552583, 2025). "An increase in MMP-11 in cancers has been associated with increased proliferation and poor disease outcome in patients." (PMID 35047406, 2021). "In the GSEA, we identified that the specific gene sets associated with the downregulation of CD8+ T cells, CD4+ T cells and B cells, which play an important role in the complete elimination of cancer cells, were linked to high MMP-11 expression." (PMID 34038440, 2021). "To explore the role of MMP11 in cancer, we took advantage of two genetic models of gain and loss of function and crossed them with the mammary gland tumor prone MMTV-PyMT strain." (PMID 32825455, 2020). "We showed previously that MMP11 functions in the regulation of whole-body metabolism through activation of the IGF1/AKT/FoxO1 signaling cascade in a non-cancer context using gain- and loss-of-function genetic-engineered mice models." (PMID 32825455, 2020). "The overexpression of MMP11 has been observed in various types of human cancers and was suggested to be associated with cancer aggressiveness and invasiveness." (PMID 31940762, 2020). "T2 specific variants were enriched in the cancer metastasis signaling (P = 4.33E‐03) including the matrix metalloproteases 11 (MMP11), low density lipoprotein receptor‐related protein 1(LRP1), mutS homolog 3 (MSH3), and son of sevenless homolog 2 (SOS2)." (PMID 30941903, 2019). "In HR+/HER2− cancers, LN+ status and expression of MMP11 and TOP2A were independently associated with the increased risk of recurrence." (PMID 28409241, 2017). "Analyses using the miRanda and Pic Tar algorithms indicated that several cancer-associated genes including MMP11, ERBB2, ERBB3, EDN1, VEGF-A, MMP14 and BCL-9L, were potential target genes of miR-125a." (PMID 22768249, 2012). "MMP11 expression in the immediate vicinity or within cancer cells has been associated with some human carcinomas and it is a consistently active partner of invading cancer cells." (PMID 15989693, 2005). "Finally, MMP11 is broadly upregulated across malignancies and associated with poor prognosis in multiple cancer types." (PMID 40607407, 2025). "Notably, we have identified similar MMP11+ mCAFs populations in other cancer types, which are also associated with poor prognosis." (PMID 40552583, 2025). "In addition, the expression levels of MMP11 can be utilized to identify patients at a higher risk of cancer recurrence." (PMID 39239548, 2024). "Mechanistically, MMP11's cancer-promoting role in CRC was linked to the expression of Slug." (PMID 39239548, 2024). "Genetic polymorphisms of MMP-11 have been found in different cancer types." (PMID 33369474, 2020). "MMP11 has been implicated to promote cancer development and progression in many malignancies." (PMID 31595150, 2019). "Moreover, elevated expression of MMP-7, -8, -9, and -11 have been described in PC tissues; two of these, MMP-7 and MMP-11, are strongly associated with poor cancer prognosis." (PMID 21625447, 2011). "Additionally, MMP11 overexpression is associated with an alteration in mitochondrial function due to increased oxidative stress and promotes a metabolic switch to aerobic glycolysis to provide metabolites for cancer cells." (PMID 37543577, 2023). "To investigate the presence of MMP11+ mCAFs across various cancer types, we performed a pan‐cancer analysis." (PMID 40552583, 2025). "Cancer-associated fibroblasts (CAF) expressed well-known markers including FAP, COL1A1, COL10A1, MMP11, and CTHRC120,21, and other genes such as INHBA, SLC12A8, F2R, and COL12A1 in various organs." (PMID 38744958, 2024).
cancer (continued). "The secretion of MMPs from M2 macrophages, particularly the high expression of MMP-11, plays a crucial role in facilitating cancer cell metastasis, with an overexpression of MMP-11 in M2 macrophages." (PMID 38713256, 2024). "MMP-11 is specifically expressed in cancer tissue, its presence in normal resting breast is undiscernible." (PMID 38438841, 2024). "Recent mining of transcriptomic databases has identified MMP11 and ADAM metallopeptidase domain 12 (ADAM12) as potential CPAs, with MMP11 exhibiting high transcript levels in 25 different types of cancers." (PMID 38707901, 2024). "Of note, MMP11 expression by TAMs can reportedly be stimulated by MMP11-overexpressing cancer cells." (PMID 39044824, 2024). "To the best of our knowledge, we are the first team to determine MMP-11 levels in OC patients, so our results will be related to other cancer types." (PMID 38892452, 2024). "Correlation analysis with immunohistochemistry findings showed that the degrees of CD4 + and CD163 + cell infiltration and IL-6 and MMP-11 expression were correlated with cancer imaging features on PET/CT." (PMID 38627864, 2024). "Immunohistochemistry assays showed that MMP11 expression level was significantly enhanced in PC tissues compared with in para-carcinoma tissues." (PMID 38572434, 2024). "Currently, there is a need to conduct further research analyzing the role of MMP-11 in cancer progression." (PMID 38203373, 2023). "MMP-11 is an important protease that is expressed in cancer cells, stromal cells, and the surrounding microenvironment." (PMID 38203373, 2023). "The role of MMP-11 in HER2-positive BC through interaction with cancer cells, monocytes, and endothelial cells is also indicated." (PMID 37798646, 2023). "The common (pan-cancer) genes are MMP11 (+), C7 (-), ANGPTL1 (-), UBE2C (+), IQGAP3 (+) and ADH1B (-)." (PMID 36802377, 2023). "MMP11 overexpression in early stages is necessary for cancer progression via inhibition of apoptosis, and promotion of invasion and metastasis." (PMID 37287543, 2023). "MMP11 can be expressed in different cancers through various enhanced expression pathways, while MMP11 expression is almost absent in normal tissues." (PMID 36756152, 2023). "Numerous recent studies consistently indicate that activated fibroblasts exert control over the progression and metastasis of cancer through their active secretory protein, comprising MMP11, MMP14, and FN1." (PMID 38057779, 2023). "We labeled cell types as endothelial cell (Endothelial, gene expression of PLVAP, KDR, PTPRB) and cancer associated fibroblasts cell (CAFs, gene expression of FAP, MMP11, PDGFRB, SFRP2, PDGFRA, ADAMTS2)." (PMID 37065499, 2023). "Using the Oncomine database, we analyzed MMP11 expression in malignant tumors and distinct subtypes using the TIMER online platform." (PMID 36756152, 2023). "Cancer-associated fibroblasts (mCAF) in matrix expressing vimentin, SMA, COL3A, COL10, and MMP11 were predominant in HGSOC tumors and were capable of inducing EMT characteristics in HGSOC cells." (PMID 37090728, 2023). "The other 11 up-regulated genes, such as FOXQ1, MMP7, MMP11, andCDH3, have been reported in previous cancer-related studies." (PMID 36434686, 2022). "The expression of cyclin D1 and MMP-11 decreased, the cycle of cancer cells was blocked, and the metastatic ability of cancer cells was inhibited." (PMID 36034798, 2022). "Consistent with this, overexpression of MMP-11 appears to play a key role in cancer invasion and other directional migration processes (i.e., migration of PGCs to the developing gonads), although its precise role in male GCTs has not been yet clarified." (PMID 36506071, 2022). "The increased expression of MMP-11 and MMP-3 further indicates that macrophage-CM can increase adipocyte delipidation and cancer association." (PMID 36551185, 2022).
cancer (continued). "Although CD200 is expressed by less than 4% of BCC cells, which exhibit a cancer stem cell phenotype, MMP11 facilitates high levels of sCD200 secretion into the TME." (PMID 36074574, 2022). "When cultured CAFs obtained from biopsy exhibited a high MMP11 gene expression, both cultured CAFs and CAFs from the corresponding prostatectomy cancer tissue also showed a high protein expression; the same occurs with a low gene expression." (PMID 35885510, 2022). "MMP11 also played an important role in the tumorigenesis, proliferation, and invasion process of other cancers." (PMID 34804973, 2021). "Matrix metalloproteinase-11 (MMP-11) promote cancer invasion and metastasis through degrading the extracellular matrix." (PMID 34038440, 2021). "This approach allowed us to identify gene transcripts that increased in cancer such as MMP11 (increase rank by 223 positions) and gene transcripts with lower expression in cancer such as ADAMTS8 (decrease rank by 196 positions)." (PMID 34732773, 2021). "The miR-139-5p/miR-139-3p/MMP11 axis seems to regulate several genes that contribute to cancer cell aggressiveness including CXCL1 and CXCL3." (PMID 33672684, 2021). "Both miRNAs were downregulated in BLCA; their restoration significantly inhibited BLCA cancer cells viability migration and invasion through targeting MMP11." (PMID 33672684, 2021). "MMP-11 (also named stromalysin 3) was found to increase cancer cell survival and implantation during the early steps of the adjacent connective tissue invasion." (PMID 33669393, 2021). "Pictilisib and AZ960 reduced the growth of cancer cell lines with high MMP-11 expression [pictilisib: r = -0.291, p = 0.04 (Pearson’s correlation) and 0.026 (Student’s t-test); AZ960: r = -0.314, p = 0.043 and 0.009]." (PMID 34038440, 2021). "Despite a weak correlation, Pictilisib reduced the growth of cancer cell lines with high MMP-11 expression." (PMID 34038440, 2021). "MMP-11 promotes cancer development by inhibiting apoptosis and enhancing the invasion of cancer cells." (PMID 33419373, 2020). "The results showed that patients with the MMP11 rs131451 “CT + TT” genotype had a higher risk (The AHR = 2.05, 95% CI = 1.12−3.754) for cancer mortality compared with the “CC” wild-type carriers." (PMID 31940762, 2020). "Further analysis found that expression of MMP11 was significantly elevated in various individual cancer stages tissue than normal breast tissues." (PMID 32291953, 2020). "In the presence of MMP-11, the activated adipocyte dedifferentiates into a preadipocyte fibroblast-like cell, which can sustain cancer cell invasion." (PMID 33339340, 2020). "Of the 10 putative CPAs identified, matrix metallopeptidase 11 (MMP11) showed the most striking expression and prevalence, being expressed at high transcript levels in 25 different cancer types." (PMID 33087697, 2020). "MMP-11 promotes cancer development by inhibiting apoptosis, and by enhancing migration and invasion of cancer cells." (PMID 33005006, 2020). "Matrix metalloproteinase (MMP)-11 is involved in extracellular matrix degradation and remodeling and plays an essential role in cancer development and metastasis." (PMID 33228130, 2020). "To conclude, at early stage of mammary gland tumor development, the presence of MMP11 decreases cell death and hence confers a survival advantage to tumors, thereby supporting cancer growth." (PMID 32825455, 2020). "For MMP11 rs738792, patients with the “CT + TT” genotype had a higher risk (AHR = 6.562, 95% CI = 1.612−26.704) for cancer death compared with the “CC” wild-type carriers." (PMID 31940762, 2020). "MMP11, a stromelysin, was significantly upregulated in all cancer types except KICH and UCEC (p = 1E-07 to 1E-122)." (PMID 31200666, 2019). "MMP11 most frequently had significant predictive values, with AUC greater than 0.9 in twelve cancers and greater than 0.95 in eight." (PMID 31200666, 2019).